PPP4C (protein phosphatase 4 catalytic subunit)
Description:
Protein phosphatase that is involved in many processes such as microtubule organization at centrosomes, maturation of spliceosomal snRNPs, apoptosis, DNA repair, tumor necrosis factor (TNF)-alpha signaling, activation of c-Jun N-terminal kinase MAPK8, regulation of histone acetylation, DNA damage checkpoint signaling, NF-kappa-B activation and cell migration. The PPP4C-PPP4R1 PP4 complex may play a role in dephosphorylation and regulation of HDAC3. The PPP4C-PPP4R2-PPP4R3A PP4 complex specifically dephosphorylates H2AX phosphorylated on Ser-140 (gamma-H2AX) generated during DNA replication and required for DNA double strand break repair. Dephosphorylates NDEL1 at CDK1 phosphorylation sites and negatively regulates CDK1 activity in interphase (By similarity). In response to DNA damage, catalyzes RPA2 dephosphorylation, an essential step for DNA repair since it allows the efficient RPA2-mediated recruitment of RAD51 to chromatin.
Synonyms: PP4C; Pp4; PP-X; PPP4; PPX; PPH3
Tractability: Antibody: its Gene Ontology location is reachable by antibodies, with high confidence. PROTAC: ubiquitination databases record sites on it; its protein half-life has been measured; a small molecule that binds it is known.
Target class: Enzyme; Hydrolase
Gene: Protein-coding gene on chromosome 16 (30,075,967 to 30,085,385, forward strand). Ensembl gene ENSG00000149923.
Subcellular location: Cytoplasm; Nucleus; Cytoplasm, cytoskeleton, microtubule organizing center, centrosome
Subcellular location (Human Protein Atlas): Nucleoplasm; Cytosol; Plasma membrane
Pathways (Reactome):
DNA Repair: Processing of DNA double-strand break ends
Gene Ontology:
Molecular function: protein binding; protein serine/threonine phosphatase activity; hydrolase activity
Biological process: regulation of double-strand break repair; regulation of double-strand break repair via homologous recombination; double-strand break repair via homologous recombination
Cellular component: chromatin; cytosol; nucleoplasm; protein phosphatase 4 complex; centrosome; cytoplasm; nucleus
Genetic constraint (gnomAD): Loss-of-function variants: 10 observed, 41.34 expected, observed/expected ratio (o/e) 0.24, 90% interval 0.15 to 0.41. The upper end of that interval is the gene's LOEUF score, 0.41, which puts it in group 1 of 6, group 1 being the genes least tolerant of losing a copy. Missense variants: 190 observed, 433.36 expected, observed/expected ratio (o/e) 0.44, 90% interval 0.39 to 0.49. Synonymous variants: 186 observed, 171.43 expected, observed/expected ratio (o/e) 1.09, 90% interval 0.96 to 1.23.
Homologues: Orthologues: chimpanzee PPP4C (100% identical), dog PPP4C (100% identical), guinea pig PPP4C (100% identical), macaque PPP4C (100% identical), mouse Ppp4c (100% identical), pig PPP4C (100% identical), rabbit PPP4C (100% identical), rat Ppp4c (100% identical), zebrafish ppp4cb (98% identical), tropical clawed frog ppp4c (96% identical), zebrafish ppp4ca (95% identical), Drosophila melanogaster Pp4-19C (92% identical), and 2 more. Paralogues in human: PPP2CA (66% identical), PPP2CB (65% identical), PPP6C (62% identical), PPP1CC (47% identical), PPP1CA (47% identical), PPP1CB (47% identical), PPP3CA (40% identical), PPP3CC (39% identical), PPP3CB (39% identical), PPP5C (36% identical), PPEF2 (34% identical), PPEF1 (32% identical).
Diseases named in the same sentence as PPP4C in open-access papers:
PPP4C is named in the same sentence as 52 diseases in open-access papers, as found by Europe PMC text mining. Sharing a sentence is not in itself a finding about the gene and the disease. The quoted sentences say what the papers report.
breast carcinoma (8 papers, 2015 to 2024). "In conclusion, the PPPCs family, especially PPP1CA and PPP4C, could be used as new biomarkers to improve diagnostic accuracy, predict prognosis and novel targets for the treatment of breast cancer." (PMID 34964699, 2022). "Although we validated the expression levels of PPP1CA and PPP4C in breast cancer tissues and their effects on the biological behavior of breast cancer cells, further investigation of their molecular mechanisms is needed." (PMID 34964699, 2022). "We found that the PPPCs family had high diagnostic accuracy for breast cancer, with PPP1CA, PPP4C and PPEF1 having the highest diagnostic accuracy." (PMID 34964699, 2022). "We also validated the changes we identified by establishing siRNA knockout models for PPP1CA and PPP4C to investigate the biological impact in breast cancer cell culture." (PMID 34964699, 2022). "We demonstrated in vitro that inhibition of PPP1CA and PPP4C expression significantly inhibited breast cancer proliferation and migration." (PMID 34964699, 2022). "PPP4C plays a prominent role in the progression of breast cancer and is used as a new biomarker to improve the accuracy of breast cancer diagnosis." (PMID 36230961, 2022). "To verify that PPP1CA and PPP4C indeed promote the development of breast cancer, we conducted in vitro experiments on these genes." (PMID 34964699, 2022). "Relevant studies have found that the abnormal expression of the PPP4C gene exists in solid tumors such as lung cancer, breast cancer, pancreatic ductal adenocarcinoma, glioma cancer, and colorectal carcinoma, and affects the biological characteristics of tumor proliferation, migration, and invasion." (PMID 38683255, 2024). "Notably, PPP4C has been distinguished as a valuable prognostic indicator and as a potential therapeutic target in breast cancer." (PMID 39026674, 2024). "Similarly, the mRNA expression level of PPP4C in 40 breast cancer patients and the protein expression level of PPP4C in 60 breast cancer patients were significantly higher in breast cancer tissues than in paracancerous tissues." (PMID 34964699, 2022). "Moreover, inhibiting the expression of PPP4C by siRNA can significantly inhibit the proliferation and migration of breast cancer cells." (PMID 36230961, 2022). "We therefore concluded that both PPP1CA and PPP4C have a significant effect on the proliferation and metastasis of breast cancer, but whether these genes lead to a worse prognosis in breast cancer needs to be supported by more clinical data." (PMID 34964699, 2022). "Inhibition of the overexpressed PPP4C in breast cancer increases cisplatin sensitivity." (PMID 33662042, 2021). "We subsequently inhibited the expression of PPP1CA and PPP4C in breast cancer cells by siRNA and observed changes in their proliferation and migration abilities, and verified through these results that these two genes played an outstanding role in the development of breast cancer." (PMID 34964699, 2022). "Two separate GEO datasets provided further confirmation of the differential expression of PPP4C in DLBCL, consistent with previous findings in colorectal cancer, lung, pancreatic ductal adenocarcinoma, and breast cancer." (PMID 38683255, 2024). "After intervention with siRNA in breast cancer cells, the mRNA expression levels and protein expression levels of PPP1CA or PPP4C in MCF-7 and MD-MB-468 cell lines were significantly decreased." (PMID 34964699, 2022). "Among the PPPCs family, PPP1CA and PPP4C played a prominent role in the progression of breast cancer, and inhibition of PPP1CA and PPP4C expression by siRNA can significantly inhibit breast cancer cells proliferation and migration." (PMID 34964699, 2022). "In the Oncomine database, when compared with normal breast tissues, PPP1CA, PPP2CA, PPP4C and PPEF1 were significantly elevated in breast cancer tissues, while PPP1CB, PPP2CB, PPP3CA, PPP3CB, PPP3CC and PPP6C were significantly decreased in breast cancer tissues." (PMID 34964699, 2022).
lung carcinoma (4 papers, 2015 to 2024). "Elevated PPP4C concentrations serve as harbingers of unfavorable prognostic outcomes, thereby fostering the proliferation and metastasis of lung carcinoma cells." (PMID 39026674, 2024). "The findings indicated a substantial difference in PPP4C expression between benign lesions and breast and lung cancer samples, pointing to a possible link between increased PPP4C expression and the development of breast and lung cancer." (PMID 38683255, 2024). "In lung cancer, elevated expression levels of PPP4C were observed, correlating with poorer patient prognoses." (PMID 39026674, 2024). "In lung cancer and colorectal carcinoma, PPP4C promoted tumorigenesis by facilitating tumor cell survival, proliferation, migration, and invasion." (PMID 37353511, 2023). "Notably, PPP4C-mediated augmentation of the ERK pathway fosters lung cancer cell proliferation and impedes apoptotic mechanisms, thereby exacerbating clinical prognosis." (PMID 39026674, 2024).
diffuse large B-cell lymphoma (2 papers, 2023 to 2024). "The significance of Protein phosphatase 4 catalytic subunit (PPP4C) in diffuse large B-cell lymphoma (DLBCL) prognosis is not well understood." (PMID 38683255, 2024).
lung adenocarcinoma (2 papers, 2023 to 2024). A carcinoma that arises from the lung and is characterized by the presence of malignant glandular epithelial cells. "Elevated PPP4C expression has been associated with poor prognostic implications for patients suffering from lung adenocarcinoma (LUAD)." (PMID 39026674, 2024). "Meanwhile, we also compared the expression of PPP4C in normal lung epithelial cell lines and lung adenocarcinoma cell lines by Western blot experiments." (PMID 39026674, 2024). "In investigating lung adenocarcinoma, a comprehensive study was conducted to assess the differential expression of PPP4C and its effects on cellular dynamics." (PMID 39026674, 2024). "Subsequent experiments across various lung adenocarcinoma cell lines were designed to clarify the role of PPP4C." (PMID 39026674, 2024). "This investigation not only casts light on the crucial role of PPP4C in lung adenocarcinoma pathogenesis but also lays the groundwork for further explorations." (PMID 39026674, 2024). "The results showed that PPP4C was significantly overexpressed in all four lung adenocarcinoma cell lines, which also laid the foundation for our subsequent cell function experiments." (PMID 39026674, 2024). "And the regulatory effect of PPP4C on lung adenocarcinoma cells was verified by differential expression assay and cell function assay." (PMID 39026674, 2024). "Nonetheless, further investigation is imperative to delineate the impact of PPP4C on the immune milieu in lung adenocarcinoma and elucidate its interplay with other oncogenic determinants." (PMID 39026674, 2024). "However, the expression dynamics, biological functions, and impact on immune cell infiltration by PPP4C in lung adenocarcinoma (LUAD) necessitate further inquiry." (PMID 39026674, 2024). "The initial stage involved quantifying PPP4C expression in lung adenocarcinoma tissue as well as in adjacent non-cancerous tissue, utilizing methods such as Western blot analysis, RT-qPCR, and immunohistochemistry." (PMID 39026674, 2024). "Given the correlation between elevated expression of the PPP4C gene and reduced survival rates in patients with lung adenocarcinoma (LUAD), as well as its ties to immune cell infiltration in the tumor environment, we developed a prognostic model based on PPP4C." (PMID 39026674, 2024).
pancreatic cancer (2 papers, 2021 to 2022). "It has been reported that the transcription level of PPP4C is higher in pancreatic cancer than in the normal pancreas and is associated with the pathogenesis and progression of pancreatic cancer." (PMID 36230961, 2022). "PPP4C was the most significantly up-regulated gene in pancreatic cancer, with a fold change of 6.153 in the dataset from Grutzmann, and was upregulated in the dataset from Logsdon and Pei." (PMID 33270085, 2021). "At the mRNA level, our work showed that PPP4C was the most significantly upregulated gene among all PPPcs in pancreatic cancer with a fold change of 6.153." (PMID 33270085, 2021). "Among all the PPPcs, the transcription levels of PPP1CA, PPP1CB, PPP3CA, PPP3CB, and PPP4C were higher in pancreatic cancer than in the normal pancreas." (PMID 33270085, 2021).
atherosclerosis (1 paper, 2022). A disease characterized by the build-up of fatty material and calcium deposition in the arterial wall resulting in partial or complete occlusion of the arterial lumen. "LCP2, EIF4EBP1, HCK, and PPP4C were demonstrated to be highly expressed, and SYNJ2 was demonstrated to be lowly expressed in atherosclerosis compared to the control group, which can be diagnostic biomarkers for patients with atherosclerosis." (PMID 35845072, 2022). "LCP2, EIF4EBP1, HCK, and PPP4C were demonstrated to be highly expressed and SYNJ2 was demonstrated to be lowly expressed in the atherosclerosis mice model." (PMID 35845072, 2022).
breast tumor (1 paper, 2023). "In breast tumor cells, PPP4C can act as either an anti-tumor factor promoting cell apoptosis through PEA15 regulation or an oncogenic factor facilitating proliferation and migration in a cell-content dependent manner." (PMID 37353511, 2023).
Infertility (1 paper, 2024). "In sum, unrepaired DNA damage in PPP4C-deficient oocytes and embryos resulted in infertility of mutant mice at earlier adulthood." (PMID 39245708, 2024).
cancer (10 papers, 2015 to 2024). A tumor composed of atypical neoplastic, often pleomorphic cells that invade other tissues. "This broad evaluation disclosed a uniform pattern of elevated PPP4C expression in numerous cancers, notably associated with adverse results, particularly in patients with liver hepatocellular carcinoma (LIHC) and kidney renal clear cell carcinoma (KIRC)." (PMID 39026674, 2024). "Our results indicate that PPP4C is a potential biomarker for specific cancer types due to its high diagnostic accuracy and significant prognostic correlation." (PMID 37353511, 2023). "Gene Ontology (GO) enrichment analysis of PPP4C-related DEGs in pan-cancer revealed that PPP4C is linked with pattern specification, morphogenesis, and tissue development, which are essential for embryogenesis." (PMID 37353511, 2023). "Additionally, PPP4C levels were significantly associated with overall survival (OS) in 15 cancer types." (PMID 37353511, 2023). "In the cohort study of The Cancer Genome Atlas (TCGA) and Genotype-Tissue Expression (GTEx), PPP4C exhibited transcriptional imbalance between normal and tumor tissues in 28 cancer types, with high diagnostic accuracy in 14 and certain accuracy in the remaining." (PMID 37353511, 2023). "Additionally, PPP4C levels in multiple cancers were closely associated with various BPs, including morphogenesis, regionalization, and pattern specification." (PMID 37353511, 2023). "These insights underscore the potential of PPP4C as a promising therapeutic target across diverse cancer types." (PMID 39026674, 2024). "Future studies should consider integrating advanced techniques such as machine learning algorithms, spatial transcriptome analysis, and further experimental validation to unravel the biological mechanisms of PPP4C in cancer." (PMID 39026674, 2024). "Our analysis revealed that the mRNA expression of PPP4C was notably elevated in multiple types of cancer tissues, including DLBCL, in comparison to their corresponding normal tissues." (PMID 38683255, 2024). "In this study, using a pan-cancer sample taken from the TCGA dataset, we first examined the PPP4C mRNA expression level." (PMID 38683255, 2024). "Prior investigations have noted an upregulation of PPP4C expression in numerous cancer types, including colorectal, breast, and pulmonary malignancies." (PMID 39026674, 2024). "First, we utilized data from the TCGA database to analyze the gene expression levels of PPP4C in various human cancer tissues and compared them with normal tissues." (PMID 38683255, 2024). "Subsequently, an exhaustive pan-cancer assessment of PPP4C was undertaken to define its biological ramifications across various cancers." (PMID 39026674, 2024). "Collectively, our pan-cancer data determined a correlation between PPP4C and canonical Wnt activation." (PMID 37353511, 2023). "In this study, we investigated PPP4C-related BPs and potential correlation between PPP4C and Wnt signaling in human pan-cancer RNA-seq profiles and X. laevis model." (PMID 37353511, 2023). "Our results highlight the biomarker role of PPP4C in multiple cancers, provide novel insights into its function in pattern specification and Wnt signaling regulation, and support the intrinsic link between embryogenesis and oncogenesis." (PMID 37353511, 2023). "Consistent with previous reports, PPP4C mRNA levels were significantly upregulated in most cancers (27/31) and decreased in LAML." (PMID 37353511, 2023). "In our study, PPP4C levels correlated with canonical Wnt activation in multiple cancers, and X. laevis Ppp4c was required for canonical Wnt responses in embryos." (PMID 37353511, 2023). "In pan-cancer study, PPP4C levels correlated with multiple BPs, such as regionalization, pattern specification, morphogenesis, metabolism, and the development of skin, keratinocyte, epidermis, and muscle tissues." (PMID 37353511, 2023).
cancer (continued). "We examined the mRNA and protein expression levels of PPP1CA and PPP4C in clinical samples and showed that both genes were expressed at significantly higher levels in cancer tissues than in paracancerous tissues." (PMID 34964699, 2022). "Both indicate a potential role of PPP4C as a cancer-promoting gene." (PMID 38683255, 2024). "In tumorigenesis, PPP4C probably behaves as an oncogenic or protective factor cell-content-dependently, as its transcription levels corresponded to different OS outcomes in various cancer types." (PMID 37353511, 2023). "Thus, we investigated the potential correlation between PPP4C and biological processes (BPs) and canonical Wnt signaling using pan-cancer analysis and Xenopus laevis (X. laevis) embryo model." (PMID 37353511, 2023). "Recent evidence suggests an important role of PPP4C in the progression of various cancers." (PMID 33270085, 2021). "In conclusion, the pervasive increase in PPP4C expression in LUAD and other cancers highlights its critical role as an indicator of poor prognosis, thereby solidifying PPP4C as a paramount prognostic marker and a prospective therapeutic target." (PMID 39026674, 2024). "In addition, PPP4C promotes the expression of matrix metallopeptidase (MMP)-2 and MMP-9 through the PI3K/AKT signaling pathway, thus promoting the invasion and metastasis of cancer cells." (PMID 34964699, 2022).